SFMBT2 (Scm like with four mbt domains 2)
Diseases named in the same sentence as SFMBT2 in open-access papers (continued):
Sharing a sentence is not in itself a finding about the gene and the disease.
prostate tumor (1 paper, 2020). "Our study may suggest that SFMBT2 a critical regulator for the infiltration of preadipocytes and TAMs into the prostate tumor microenvironment." (PMID 32971847, 2020). "In this study, we investigated whether SFMBT2 regulates cell infiltration into the prostate tumor microenvironment, which has a critical role in metastasis." (PMID 32971847, 2020).
tumor (14 papers, 2016 to 2026). "What’s more, the downregulation of SFMBT2 was found to advance the infiltration of tumor associated macrophages (TAMs) in prostate cancer." (PMID 38225273, 2024). "The expression of SFMBT2 increased after tumorigenesis, and the high levels of SFMBT2 attempted to curb tumor development." (PMID 38734627, 2024). "The expression detection manifested the downregulation of circ-SFMBT2 and upregulation of miR-107 in tumor tissues of sh-circ-SFMBT2 group relative to sh-NC group." (PMID 34530825, 2021). "Using a tumor xenograft model, we further confirmed SFMBT2-mediated infiltration of preadipocytes and TAMs." (PMID 32971847, 2020). "If SFMBT2 level was high enough, then the tumor was blocked at an early stage." (PMID 38734627, 2024). "IHC assay demonstrated that the protein levels of SLC1A5, Ki67 and MMP9 in tumor tissues were suppressed by the silence of circ-SFMBT2, indicating that circ-SFMBT2 could promote tumor proliferation and metastasis in mice." (PMID 34530825, 2021). "The functional research of circ-SFMBT2 in vivo was performed by xenograft tumor assay." (PMID 34530825, 2021). "In the following experiments, we investigated whether knockdown of SFMBT2 induces tumor metastasis in vivo." (PMID 27340776, 2016). "SFMBT2 exerted an anti-tumor role in clear cell RCC cells, and HDAC3-mediated deacetylation promoted SIAH1-controlled ubiquitination of SFMBT2." (PMID 38734627, 2024). "RP11-704M14.1, SFMBT2-4:1, IRAIN, TET2 function as tumor suppressors in AML." (PMID 31681586, 2019). "If SFMBT2 level was not high enough, then the tumor continued to develop to an advanced stage." (PMID 38734627, 2024).
cancer (6 papers, 2016 to 2026). A tumor composed of atypical neoplastic, often pleomorphic cells that invade other tissues. "The SFMBT2 protein is a Polycomb group protein implicated in transcriptional regulation and cancer biology." (PMID 41809030, 2026). "However, it has been found that SFMBT2 levels positively correlate with survival rate in various types of cancer such as breast (GEO accession; GSE21653, P value; 0.0785), colon (GEO accession; GSE17538, P value; 0.068), and astrocytic gliomas (GEO accession; GSE18166, P value; 0.0788)." (PMID 27340776, 2016). "SFMBT2 interacts with YY1 and repressive histone marks to repress gene expression of matrix metalloproteinases (MMPs), which are critical for cancer cell migration and invasion." (PMID 32971847, 2020). "SFMBT2 expression was downregulated in clear cell RCC patients with advanced stages, but it was highly expression in whole clear cell RCC specimens than paired para-carcinoma tissues (the data was not shown)." (PMID 38734627, 2024).
infection (1 paper, 2024). The state of being infected such as from the introduction of a foreign agent such as serum, vaccine, antigenic substance or organism. "Similarly, transwell assay displayed that infection of SFMBT2-expressed lentivirus led to decreased invasive ability, and SFMBT2 silencing exacerbated invasion of 786-O and 769-P cells." (PMID 38734627, 2024).
neurodevelopmental disorder (1 paper, 2013). A behavioral and cognitive disorder with onset during the developmental period that involves impaired or aberrant development of intellectual, motor, or social functions. "Furthermore, ∼20% of the altered ncRNAs mapped to three imprinted regions (Snrpn-Ube3a, Dlk1-Dio3 and Sfmbt2) that showed differential methylation and have been previously implicated in neurodevelopmental disorders." (PMID 23580197, 2013).
SFMBT2 also shares sentences with these, for which no sentence is quoted: cerebral artery (1 paper); clear cell renal cell carcinoma (1); esophageal cancer (1); liver cancer (1); non-small cell lung carcinoma (1); opioid dependence (1); Parkinson disease (1).